SEMA3A (semaphorin 3A)
Diseases named in the same sentence as SEMA3A in open-access papers (continued):
Sharing a sentence is not in itself a finding about the gene and the disease.
Autoimmunity (3 papers, 2012 to 2025). The occurrence of an immune reaction against the organism's own cells or tissues. "With all this in mind, we assumed that the effect of Sema3A on the metabolism of T cells in health and autoimmunity should be assessed." (PMID 41303643, 2025). "In addition, co-culture of activated B cells of SLE patients with sema3A reduced the expression of TLR-9 in these B cells, thus suggesting that sema3A is a modulator in reducing autoimmunity." (PMID 25978359, 2015). "Therefore, when sema3A expression is altered auto-reactive B cells escape apoptosis and survive to overproduce autoantibodies, thus contributing to autoimmunity in SLE." (PMID 22697500, 2012). "In a seminal study, our group reported Sema3A serum levels to be significantly lower in SLE and RA patients and that its reduced activity may tip the balance toward autoimmunity." (PMID 41303643, 2025). "Indeed, it was demonstrated in the present study that the addition of sema3A, in vitro, to B cells of SLE patients, significantly reduced ODN-CpG induced TLR-9 expression in memory B cells, supporting sema3A as a regulator of autoimmunity in SLE." (PMID 22697500, 2012).
brain injury (3 papers, 2017 to 2022). Acute and chronic (see also brain INJURIES, CHRONIC) injuries to the brain, including the cerebral hemispheres, CEREBELLUM, and brain STEM. "One study investigated the association between SEMA3A, traumatic brain injury and osteogenesis and proposed the role of SEMA3A in facilitating fracture healing in traumatic brain injury." (PMID 29371932, 2017). "MiR‐30b‐5p is also suggested to exert neuroprotective effects post traumatic brain injury by targeting SEMA3A." (PMID 36282532, 2022).
Cerebral ischemia (3 papers, 2010 to 2024). Restriction of arterial blood supply to the brain associated with insufficient oxygenation to support the metabolic requirements of the tissue. "The only protein of the semaphorin class so far associated with cerebral ischemia is Semaphorin 3A, which was reported to be temporarily upregulated after MCAO, and induced after 14 d in the perilesional area of an infarct in the barrel cortex together with its receptor neuropilin I." (PMID 20505770, 2010). "Semaphorin 3A, a gene in the same family and located in the same chromosome of Semaphorin 3E, was nominally associated (second top hit) with HT in the original GWAS, and it has been related to vascular permeability of the blood-brain barrier and brain damage after cerebral ischemia in murine models." (PMID 38103737, 2024).
diabetic macular edema (3 papers, 2017 to 2025). "SEMA3A levels have been reported to be significantly elevated in the vitreous fluid of patients with diabetic macular edema and proliferative diabetic retinopathy (PDR) via NRP1." (PMID 34248841, 2021). "An alternative strategy to prevent ocular vessel leakage may involve targeting both VEGF164 and SEMA3A signaling via NRP1, in particular in conditions where SEMA3A exacerbates VEGF-induced leakage, as has been proposed for the early phase of diabetic macular edema." (PMID 28289053, 2017).
Infertility (3 papers, 2014 to 2024). "Various mutations, polymorphisms, and alternatively spliced variants of SEMA3A have been associated with infertility." (PMID 38541683, 2024). "Accordingly, loss-of-function for molecules, such as SEMA3A that control olfactory or vomeronasal axon-patterning perturbs GnRH neuron migration, leads to delayed or absence of pubertal maturation and infertility." (PMID 34721574, 2021). "Some studies reported that a particular semaphorin, semaphorin 3A, encoded by human SEMA3A, on chromosome 7p12.1, if mutated both in humans and mice, could lead to abnormal migration of GnRH neurons to the hypothalamus, leading to hypogonadism and infertility." (PMID 25254043, 2014).
liver fibrosis (3 papers, 2022 to 2024). "Next, we investigated the genotype frequency and allele distribution of selected SEMA3A, SEMA4A and SEMA5A SNPs and the possible association between the SNPs, NAFLD and liver fibrosis." (PMID 36551769, 2022).
multiple myeloma (3 papers, 2008 to 2019). "For example, when VEGF165-stimulated multiple myeloma ECs were exposed to SEMA3A, a time-dependent decrease of endogenous VEGF165 mRNA was observed." (PMID 18781179, 2008).
oral cancer (3 papers, 2012 to 2025). "Both in vivo and in vitro results in a xenograft oral cancer model showed that SEMA3A overexpression halted tumour cell growth by inhibiting angiogenesis." (PMID 40318008, 2025). "Overexpression of Sema3A in oral cancer cells drastically suppresses the growth of oral cancer by inhibiting angiogenesis." (PMID 28683823, 2017). "Western blot was used to assess the protein expression levels of Sema3A in the oral cancer cell line SCC-9." (PMID 28683823, 2017). "Sema3A reduces VEGFR2 phosphorylation in oral cancer, and further inhibits the phosphorylation of Src and FAK, downstream of VEGF/VEGFR2." (PMID 28683823, 2017). "In human squamous cell carcinoma of the tongue, Sema3A amounts are low, with higher expression levels prolonging the survival of patients with oral cancer." (PMID 28683823, 2017). "The results showed that Sema3A was efficiently expressed in oral cancer cells after lentiSema3A transfection." (PMID 28683823, 2017). "Further studies are needed to further assess the relationship between Sema3A and chemotherapy targeting anti-angiogenesis in oral cancer." (PMID 28683823, 2017). "Further studies are needed to evaluate the effects of Sema3A on the oral cancer in orthotopic model." (PMID 28683823, 2017). "In the present study, we demonstrated that Sema3A overexpression inhibits the phosphorylation of VEGFR2 in oral cancer tissues." (PMID 28683823, 2017). "Our results demonstrated that overexpression of Sema3A in oral cancer cells drastically suppressed tumor growth by inhibiting angiogenesis." (PMID 28683823, 2017). "Interestingly, the axonal sprouting inhibitor semaphorin 3A (Sema3A), a potent suppressor of tumor angiogenesis in various cancer models, is lowly expressed in human oral cancer." (PMID 28683823, 2017). "We confirmed here that Sema3A is lowly expressed in the oral cancer cell line SSC-9." (PMID 28683823, 2017). "The expression of Sema3A in oral cancer cells was further confirmed by Western blot." (PMID 28683823, 2017). "In this study, by lentiviral-mediated overexpression of Sema3A in oral cancer cells, we assessed whether Sema3A decreases the growth of oral cancer by inhibiting angiogenesis, further exploring the mechanism of angiogenesis inhibition by Sema3A." (PMID 28683823, 2017). "Thus, Sema3A mediates inhibition of both tumorigenesis and angiogenesis in Xenograft oral cancer mode of mice." (PMID 28683823, 2017). "Low Sema3A expression has been described in oral cancer tissues." (PMID 28683823, 2017). "Because tumor cells also express VEGFR2, in addition to inhibit angiogenesis, overexpression of Sema3A in oral cancer cells may inhibit tumor growth by direct effect to the tumor in our Xenograft model of oral cancer." (PMID 28683823, 2017). "The results showed that Sema3A significantly inhibited oral cancer angiogenesis (P < 0.01)." (PMID 28683823, 2017). "Thus, we hypothesized that overexpression of Sema3A in human oral cancer cells may have potential therapeutic effects." (PMID 28683823, 2017). "Interestingly, Sema3A drastically inhibited oral cancer growth in this xenograft model." (PMID 28683823, 2017). "In the present study, we found that overexpression of Sema3A in oral cancer cells using a lentiviral vector inhibited angiogenesis and drastically suppressed tumor growth, suggesting that Sema3A may be a potential target for the treatment of oral cancer in clinical practice." (PMID 28683823, 2017). "The results showed that Sema3A inhibited the phosphorylation of VEGFR2; in addition, phosphorylation of the downstream genes Src and FAK in oral cancer was reduced, which results in tumor angiogenesis inhibition." (PMID 28683823, 2017).
Osteopenia (3 papers, 2016 to 2024). Osteopenia is a term to define bone density that is not normal but also not as low as osteoporosis. "Indeed, it is now known that Semaphorin 3B promotes osteoclastogenesis and osteopenia in a mouse model and that Semaphorin 3A exerts an osteoprotective effect by suppressing bone resorption and increasing bone formation." (PMID 26910109, 2016).
pancreatic neuroendocrine tumor (3 papers, 2017 to 2021). Pancreatic endocrine tumor, also known as pancreatic neuroendocrine tumor (PNET), describes a group of endocrine tumors originating in the pancreas that are usually indolent and benign, but may have the potential to be malignant. "The pro-invasive and pro-metastatic resistance detected upon angiogenesis reduction by the small-molecule tyrosine inhibitor sunitinib in pancreatic neuroendocrine tumors (PNETs) can be overwhelmed by SEMA3A expression." (PMID 32842711, 2020).
peripheral nerve injury (3 papers, 2013 to 2019). Injury to a peripheral nerve. "Previous reports have shown activation of Sema3A in response to peripheral nerve injury." (PMID 30862799, 2019). "Down-regulated expression of Sema3a mRNA in adult neurons was observed in post-peripheral nerve injury 17, 18 and down-regulation of semaphorin expression could result in a more permissive environment for axonal regeneration and sprouting." (PMID 23711091, 2013).
squamous cell carcinoma (3 papers, 2012 to 2024). A carcinoma arising from squamous epithelial cells. "A multi‐omics study identified SEMA3A as a prognostic biomarker in squamous cell carcinoma." (PMID 39177014, 2024). "Key words:Semaphorin 3A, neuropilin 1, tongue, squamous cell carcinoma." (PMID 22926477, 2012).
tongue cancer (3 papers, 2012 to 2020). A malignant neoplasm affecting the tongue. "In conclusion, in this study, we observed the over-expression of NRP1 and loss of SEMA3A expression in human tongue cancer." (PMID 22926477, 2012). "However, loss of SEMA3A expression was observed in tongue cancer compared with normal tongue epithelium." (PMID 22926477, 2012). "SEMA3A expression was also significantly downregulated in tongue cancer and correlated with nodal metastasis." (PMID 29649113, 2018). "Statistical analyses were performed using Chi-squared and Spearman tests and Kaplan-Meier analysis.Results: SEMA3A was significantly down-regulated in tongue cancer compared with normal tongue (P=0.025), while NRP1 was over-expressed in tumours (P<0.001)." (PMID 22926477, 2012). "The discrepant change in SEMA3A signalling in tongue cancer in our study indicates the important role of this protein in the development of the disease." (PMID 22926477, 2012). "Moreover, lower expression of SEMA3A correlated with poor prognosis, suggesting a tumour suppressor function for SEMA3A in human tongue cancer." (PMID 22926477, 2012). "Therefore, we focused on the expression of SEMA3A and its receptor NRP1 in tongue cancer and the potential contribution of these molecules in the prediction of prognosis." (PMID 22926477, 2012). "Scores for the NRP1/SEMA3A ratio of ≥1 predicted shorter survival (P=0.045).Conclusions: Aberrant expression of SEMA3A and its receptor NRP1 might be involved in the development of tongue cancer and might be useful prognostic markers in this tumour type." (PMID 22926477, 2012).
ventricular tachycardia (3 papers, 2013 to 2016). A disorder characterized by an electrocardiographic finding of three or more consecutive complexes of ventricular origin with a rate greater than a certain threshold (100 or 120 beats per minute are commonly used). "Interestingly, murine cardiac-specific SEMA3A under-expression results in sinus bradycardia and SEMA3A over-expression in a susceptibility to ventricular tachycardia and sudden death, putatively due to differences in the pattern of cardiac innervation." (PMID 23593042, 2013). "For instance, studies in mice and humans have revealed the implication of Sema3a-mediated sympathetic axonal guidance and patterning in the development of ventricular tachycardia and SCD." (PMID 26857994, 2016).
acute myeloid leukemia (2 papers, 2019). Acute myeloid leukemia (AML) is a group of neoplasms arising from precursor cells committed to the myeloid cell-line differentiation. "In acute myeloid leukemia, high expression of VEGFA was identified as an oncogenic factor, whose function may be reversed by SEMA3A competing for neuropilin." (PMID 31552163, 2019). "It was furthermore shown that SEMA3A may partially reverse VEGF-induced proliferation of acute myeloid leukemia (AML) cells, and the combined administration of VEGF inhibitors and recombinant SEMA3A was suggested as potential treatment for AML patients." (PMID 31143707, 2019).
allergic conjunctivitis (2 papers, 2018 to 2022). "Treating mice with allergic conjunctivitis with sema3A efficiently suppressed Th2 cytokine release in mice." (PMID 35769512, 2022). "It is reported that administration of sema3A alleviates experimental allergic conjunctivitis." (PMID 35769512, 2022). "Tanaka and Alfonso demonstrated that Sema3a suppressed the release of Th2-related cytokines (IL-5, IL-13 and IL-4) and inflammatory cytokines (IFN-α, IL-17 and TNF-α) but increased levels of the cytokine IL-10 in experimental allergic conjunctivitis and autoimmune arthritis models." (PMID 29975739, 2018).
allergic disease (2 papers, 2022 to 2023). An immune response that occurs following re-exposure to an innocuous antigen, and that requires the presence of existing antibodies against that antigen. "The ratio of Ni allergy-induced ear thickness to the control ear thickness, which represents the degree of thickening of ears, was significantly lower in the Sema3A cKO group than in the control group 24 h and 48 h post-Ni re-challenge." (PMID 35798870, 2022). "In other words, when inducing Ni allergy, the ear swelling in Sema3A cKO mice was less severe than that in the control mice." (PMID 35798870, 2022). "In the H&E staining of Ni allergy-induced ear tissue of Sema3A cKO mice, infiltrated inflammatory cells could be observed, but the edema was less severe than in the control mice." (PMID 35798870, 2022).
amyotrophic lateral sclerosis (2 papers, 2017 to 2024). Amyotrophic lateral sclerosis (ALS) is a neurodegenerative disease characterized by progressive muscular paralysis reflecting degeneration of motor neurons in the primary motor cortex, corticospinal tracts, brainstem and spinal cord. "Sema3A regulation was furthermore associated with Amyotrophic Lateral Sclerosis (ALS)." (PMID 37728580, 2024). "Semaphorin 3A (SEMA3A) expression is up-regulated in TSCs at the NMJ following experimental denervation of the muscle (BotoxA-induced paralysis or crush injury to the sciatic nerve) or in the motor neuron disease amyotrophic lateral sclerosis." (PMID 28103314, 2017). "In conclusion, the presence of a mutant isoform of SEMA3A, with decreased signaling capacity, does not alter the amyotrophic lateral sclerosis related decrease in motor function." (PMID 28103314, 2017). "The chemorepulsive protein semaphorin 3A (SEMA3A) is selectively up-regulated in TSCs on fast-fatigable muscle fibers following experimental denervation of the muscle (BotoxA-induced paralysis or crush injury to the sciatic nerve) or in the motor neuron disease amyotrophic lateral sclerosis (ALS)." (PMID 28103314, 2017).
Anxiety (2 papers, 2021 to 2022). Intense feelings of nervousness, tension, or panic often arise in response to interpersonal stresses. "In this study, we found that the postpartum anxiety and depressive symptoms, as well as the increased expression of hippocampal Sema3A and decreased phosphorylation of GSK3β caused by gestational stress could be reversed by systemic administration EGCG." (PMID 36776771, 2022).
asthma (2 papers, 2015 to 2019). "In earlier studies, we found that reduced sema3A concentration in the serum of asthma patients as well as reduced expression by Treg cells correlates with asthma disease severity." (PMID 30967873, 2019). "To conclude, we find that in this asthma model, sema3A functions as a potent suppressor of asthma related inflammation that has the potential to be further developed as a new therapeutic for the treatment of asthma." (PMID 30967873, 2019). "We find that in this asthma model, sema3A functions as a potent suppressor of asthma related inflammation that in addition inhibits asthma associated angiogenesis." (PMID 30967873, 2019). "To find out if sema3A can be of benefit to asthma patients, we evaluated the effect of sema3A injection in a mouse model of asthma." (PMID 30967873, 2019). "With this in mind we have evaluated in the present study the therapeutic immune-modulatory effects of sema3A following its injection into mice in which we have induced asthma using ovalbumin (OVA) adjuvant." (PMID 30967873, 2019). "Thus, new anti-angiogenic compounds such as sema3A are needed in order to control remodeling in asthma." (PMID 30967873, 2019). "We have found that low serum levels of sema3A are correlated with severe asthma." (PMID 30967873, 2019).
bladder tumor (2 papers, 2021 to 2024). "These patients showed a light expression of Sema3A in their bladder mucosa, similar to patients with no history of UC, despite the fact that their bladder tumor samples prior to therapy highly expressed Sema3A." (PMID 33546237, 2021).
brain tumor (2 papers, 2020 to 2025). "While SEMA3F suppresses U87 migration via the NRP2/PLXNA1 receptor complex, SEMA3A suppresses brain tumor stem cell proliferation but enhances migration through NRP1/PLXNA1 complex, and PLXNA1-knockdown reduced the growth of GBM in an mice model." (PMID 40533501, 2025). "We hypothesized that Sema3A directly inhibits brain tumor stem cell (BTSC) proliferation and drives invasion via Neuropilin 1 (Nrp1) and Plexin A1 (PlxnA1) receptors." (PMID 33302912, 2020).
cardiac arrest (2 papers, 2013 to 2021). Cessation of breathing and/or cardiac function. "Indeed, SEMA3A has been indirectly implicated in cardiac arrest and ventricular fibrillation by affecting the cardiac sympathetic innervation." (PMID 34743696, 2021).
cardiac hypertrophy (2 papers, 2021 to 2023). "Immunoblotting and enzyme‐linked immunosorbent assay (ELISA) analyses revealed that Sema3A expression was upregulated in the heart tissue and serum of mice 4 weeks after cardiac hypertrophy was induced through TAC." (PMID 37310417, 2023). "Overall, these findings demonstrated that Sema3A levels in MiVECs are elevated during pressure overload‐induced myocardial hypertrophy and that this secretory protein may be involved in microvascular rarefaction." (PMID 37310417, 2023).
cognitive deficits (2 papers, 2022). "After correction for histopathological grade P-STAT5b, CD163, CD3, and Semaphorin-3A expression were independently associated with cognitive deficits in different domains." (PMID 35148403, 2022). "This is consistent with previous findings that Sema3A accumulation might contribute to neurodegeneration and induce cognitive impairment." (PMID 36159327, 2022).